IFNAR1 (interferon alpha and beta receptor subunit 1)
Diseases named in the same sentence as IFNAR1 in open-access papers (continued):
Sharing a sentence is not in itself a finding about the gene and the disease.
Chlamydia infection (1 paper, 2015). "We surmise there must be some host cell or Chlamydia-induced component early during Chlamydia infection that either causes the preferential induction of IFNα through IFNAR1, or shuts off the ability of this pathway to induce IFN-β." (PMID 25798928, 2015). "IFNAR1 transcription remains consistent throughout the course of Chlamydia infection; however, there was a significant down-regulation in the transcription of IFNAR1 between 6 h and 8 h post-infection." (PMID 25798928, 2015).
chronic pancreatitis (1 paper, 2014). A chronic inflammatory process causing damage and fibrosis of the pancreatic parenchyma. "Presented here results demonstrate that inability to stimulate IFNAR1 ubiquitination in the Ifnar1SA knock-in mice renders them highly susceptible to numerous inflammatory syndromes including acute and chronic pancreatitis, and autoimmune and toxic hepatitis." (PMID 24480543, 2014).
COPA syndrome (1 paper, 2025). "The use of novel therapies, specifically targeting type I IFN signalling, such as the monoclonal anti-IFNAR1 antibody anifrolumab, will help in discriminating the IFN-dependent and independent pathogenesis of COPA syndrome." (PMID 41395910, 2025).
Crohn disease (1 paper, 2009). A gastrointestinal disorder characterized by chronic inflammation involving all layers of the intestinal wall, noncaseating granulomas affecting the intestinal wall and regional lymph nodes, and transmural fibrosis. "Two emerge with highly significant GRAIL scores: rs8178556 on chromosome 21 (IFNAR1, ptext = 1.7×10−4) and rs12928822 on chromosome 16 (SOCS1, ptext = 8.2×10−4) suggesting these independent regions may lead to novel associated SNPs for Crohn's disease." (PMID 19557189, 2009).
cryptococcal infection (1 paper, 2015). "We further examined the effect of IFNAR1 deficiency on the Th2 response by measuring the production of IL-4, IL-5, and IL-13 in the lungs on day 3, 7, 14, and 28 after cryptococcal infection." (PMID 26384031, 2015).
dacryoadenitis (1 paper, 2018). Inflammation and enlargement of the lacrimal gland. "To address the role of type I IFN signaling in the development of dacryoadenitis, we quantified dacryoadenitis in wild-type and Ifnar1-deficient NOD mice." (PMID 30347820, 2018). "Little to no dacryoadenitis developed in either wild-type or Ifnar1-deficient female NOD mice." (PMID 30347820, 2018). "Notably, Ifnar1-deficient NOD mice did not develop dacryoadenitis." (PMID 30347820, 2018).
deficiency (1 paper, 2022). "Globally, autosomal recessive IFNAR1 deficiency is a rare inborn error of immunity underlying susceptibility to live attenuated vaccine and wild-type viruses." (PMID 35442418, 2022). "This highlights the much higher risk of death in unvaccinated populations due to vaccine-preventable disease than of IFNAR1 deficiency leading to severe complications of MMR vaccination." (PMID 35442418, 2022). "Rapid, cost-effective, and accessible diagnostic methods will be required, because IFNAR1 deficiency is difficult to recognize clinically due to the existence of both nonspecific and unknown presentations." (PMID 35442418, 2022). "The early diagnosis of IFNAR1 and other type 1 IFN deficiencies not only would be of direct benefit to the affected individuals, but could also potentially increase confidence in vaccination, thereby resulting in better protection of the community." (PMID 35442418, 2022).
Ebola (1 paper, 2019). "Ifnar1-/- mice have been used previously for other viral animal models, including Ebola, Zika, West Nile (WNV) and severe fever with thrombocytopenia syndrome (SFTSV) viruses." (PMID 31194854, 2019).
endometrial cancer (1 paper, 2022). Primary or metastatic malignant neoplasm involving the endometrium (mucous membrane that lines the endometrial cavity). "In addition to the classical JAK‐STAT pathway, IFNAR1 negatively regulates the STAT3 pathway upon binding to IFN1 to accelerate metastasis in endometrial cancer." (PMID 35244291, 2022).
Ewing sarcoma (1 paper, 2023). A small round cell tumor that lacks morphologic, immunohistochemical, and electron microscopic evidence of neuroectodermal differentiation. "Synergistic induction of CXCL9/CXCL10 was completely ablated by IFNGR1 depletion, and partly inhibited by IFNAR1 depletion, indicating that Ewing sarcoma–intrinsic signaling through both pathways contributes to this feedforward loop." (PMID 37615015, 2023).
Gastric Metaplasia (1 paper, 2022). Intestinal metaplasia of the gastric mucosa is an intermediate precancerous gastric lesion in the gastric cancer cascade from chronic gastritis and atrophy to dysplasia and adenocarcinoma. "To test whether gastric metaplasia was dependent on IFNAR1 signaling, we treated Ifnar1–/– mice with HD-Tam." (PMID 35132959, 2022).
Hypertension (1 paper, 2016). The presence of chronic increased pressure in the systemic arterial system. "This analysis allowed us to identify 6 well-annotated genes: RTP4, FXYD6, GDF11, IFNAR1, NOX3, and HLA-DQ2, associated with dynamics of future hypertension incidence." (PMID 27980621, 2016). "Two of them, IFNAR1 and NOX3 were previously implicated in pathogenesis of hypertension." (PMID 27980621, 2016).
injury (1 paper, 2020). Damage inflicted on the body as the direct or indirect result of an external force, with or without disruption of structural continuity. "The upregulation of MX1 and CXCL11 at mRNA and of STAT1 at the protein level in the HIVgp120tg hippocampus as well as the complete abrogation of the increases in the absence of IFNAR1 confirmed the type I IFN response we previously observed in this model system of HIV-associated brain injury." (PMID 32727588, 2020).
medulloblastoma (1 paper, 2025). A malignant, invasive embryonal neoplasm arising from the cerebellum. "All immune cells express receptors for TNF-alpha (TNFRSF1A and TNFRSF1B) and IFN alpha (IFNAR1 and IFNAR2) and are enriched for these pathways, indicating that all these immune cell types are primed to respond to secreted TNF-alpha and IFN alpha in the medulloblastoma TME." (PMID 40240536, 2025).
memory impairment (1 paper, 2020). "Indeed, the present study provides evidence that IFNAR1 contributes to HIVgp120-induced neuronal injury and neurocognitive and memory impairment." (PMID 32727588, 2020).
metastatic melanoma (1 paper, 2022). A melanoma that has spread from its primary site to another anatomic site. "Although all the IFNA transcripts were barely detectable, high levels of IFNAR1 and IFNAR2 expression were observed in both primary and metastatic melanoma." (PMID 35145233, 2022).
Miscarriage (1 paper, 2020). A pregnancy that ends at a stage in which the fetus is incapable of surviving on its own, defined as the spontaneous loss of a fetus before the 22th week of pregnancy. "The miscarriage rate was significantly higher in Ifnar1−/− females crossed to Ifnar1−/− males than in those crossed to WT males (50% versus 23%)." (PMID 32628667, 2020).
Multiple Organ Failure (1 paper, 2021). A progressive condition usually characterized by combined failure of several organs such as the lungs, liver, kidney, along with some clotting mechanisms, usually postinjury or postoperative. "Multiple organ failure observed in the patient presented could be related to the triple gene dose of four interferon receptors (IFNAR1, IFNAR2, IFNGR2, and IL10RB) located at 21q22.11." (PMID 34760326, 2021).
myositis (1 paper, 2019). "Thus, paw inflammation, acral necrosis, myositis, and proinflammatory cytokine/chemokine production was absent in hSTING-N154S mice lacking the Ifnar1." (PMID 31221625, 2019).
Nephropathy (1 paper, 2022). A nonspecific term referring to disease or damage of the kidneys. "The increased gene expression of some of these ISGs, IFNβ, and IFNAR1/2, taken as reporters of the TI-IFN pathway activation, were validated by PCR in mice with both FAN and LPS-induced nephropathy (LPSN)." (PMID 36386242, 2022).
oral squamous cell carcinoma (1 paper, 2024). "Studies in other cancers have shown that the use of IFN-α, a ligand that activates IFNAR1, can promote stem-like properties in oral squamous cell carcinoma (OSCC) cells, whereby tumor xenografts treated with IFN-α increased the expression of stemness markers and tumor growth." (PMID 39457004, 2024).
Osteochondroma (1 paper, 2024). A common, benign cartiliginous neoplasm arising from the metaphysis of bone. "Expression of Ifnar1 was detected in osteochondromas, and palovarotene treatment did not upregulate the expression level." (PMID 39062860, 2024).
placental insufficiency (1 paper, 2018). Failure of the placenta to deliver an adequate supply of nutrients and oxygen to the fetus. "Thus, it is plausible that the reduction of the parasite burden attributable to fetal IFNAR1 is not large enough to significantly prevent placental insufficiency and the subsequent detrimental effects on the fetus." (PMID 29440369, 2018).
prion disease (1 paper, 2019). A transmissible disease that is caused by a protein that is able to induce abnormal folding of normal cellular proteins, leading to characteristic spongiform brain changes, which are associated with neuronal loss without an inflammatory response. "In the current study, we assessed expression of IFN‐I in murine prion disease (ME7) and examined the contribution of the IFN‐I receptor IFNAR1 to disease progression." (PMID 30680794, 2019). "Prion disease‐induced neurological impairments were manifest from about 17 weeks in wild‐type ME7 animals, as previously reported, and the onset of these impairments was delayed by approximately 2 weeks in IFNAR1−/− ME7 animals." (PMID 30680794, 2019). "Here, IFNAR1 deficiency did not impact upon Il1b mRNA levels and decreased Il10 and Trem2 expression suggesting that canonical IFNAR‐STAT1/2 signaling is dominant in ME7 prion disease." (PMID 30680794, 2019). "Therefore, the impact of IFNAR1 on the progression of ME7 prion disease is independent of altered PrPSc deposition." (PMID 30680794, 2019).
Psoriasiform dermatitis (1 paper, 2016). A skin abnormality characterized by redness and irritation, with thick, red skin that displays flaky, silver-white patches (scales). "Analysis of gene-modified mice suggests that the initiation of IMQ-induced psoriasiform dermatitis involves the TLR7- and IFNAR1-mediated signaling cascades, whereas the activation of CD4+ Teff cells through costimulation by APCs contributes to the disease progression." (PMID 27075414, 2016).
respiratory failure (1 paper, 2017). The significant impairment of gas exchange within the lungs resulting in hypoxia, hypercarbia, or both, to the extent that organ tissue perfusion is severely compromised. "Thus, the higher and progressively increasing bacterial burden and tissue injury in the lung of K. pneumoniae-infected Ifnar1-deficient mice suggest that these mice ultimately suffer respiratory failure." (PMID 29112952, 2017).
staphylococcal pneumonia (1 paper, 2022). Pneumonia caused by infections with bacteria of the genus staphylococcus, usually with staphylococcus aureus. "Indeed, type I IFNs have been reported to have dual effects on S. aureus infections, with IFN-α/β receptor (IFNAR) deficient mice showing decreased mortality in a staphylococcal pneumonia model, while an anti-IFNAR1 subunit antibody has been reported to increase lung S. aureus burden." (PMID 36532419, 2022).
Urea (1 paper, 2025). "Notably, IFNAR1, TBK1, and TRAF6-downstream components of cGAS-STING signaling -were significantly upregulated in the Urea + OGD group, suggesting engagement of DNA damage-driven inflammatory mechanisms." (PMID 41286951, 2025).
infection (661 papers, 2009 to 2026). The state of being infected such as from the introduction of a foreign agent such as serum, vaccine, antigenic substance or organism. "By 10 days post-infection, IFNAR1 deficiency resulted in significantly increased bacterial loads in skin and heart tissues, while joint burdens remained unaffected." (PMID 41727126, 2026). "By knocking out the Ifnar1 gene, these mice lack the receptor necessary for cells to respond to type I IFNs, thereby exhibiting heightened susceptibility to infection by viruses, including DENV." (PMID 39817192, 2025). "Infection with NH/P68 also caused down-regulation of IFNAR1 and NLRP3 receptors, MYD88 adaptor proteins, as well as other molecules involved in modulating receptor signaling pathways (JUN, PELI1, TBK1, and TICAM2)." (PMID 40530033, 2025). "A129 mice, which are deficient in the IFN-α/β receptor (IFNAR1−/−), have been shown to be susceptible to peripheral infection with wild-type (WT) YFV strains, such as Asibi and Angola73." (PMID 41157597, 2025). "Following infection, incremental weight loss and additional clinical signs listed previously were recorded in Ifnar1-/- and Stat1-/- mice." (PMID 40694555, 2025). "In contrast, MyD88 and IFNAR1 KO mice exhibited resistance to lethal infection with the mouse-adapted SARS-CoV-2 Delta variant." (PMID 39652608, 2024). "The clinical phenotype of both DOCK8 and IFNAR1 deficiencies includes susceptibility to infection with various viruses." (PMID 39098944, 2024). "Antiviral medication should be initiated, if indicated, and a role for exogenous IFN-γ has been explored in the acute phase of infection in a patient with IFNAR1 deficiency with severe COVID-19 pneumonia." (PMID 36976641, 2023). "While WT mice efficiently control acute infection, Ifnar1-/- mice are highly susceptible depending on the viral dose." (PMID 37065193, 2023). "Caution should be used when considering anti-IFNAR1 treatment in patients with a history of chronic or recurrent infections or at high risk for infections." (PMID 36119023, 2022). "A common method of increasing the susceptibility to infection in wild-type mice is to utilize an IFNAR1 blocking antibody." (PMID 34410903, 2021). "Nevertheless, these findings reveal that i.d. infection can cause lethal disease in Ifnar1-/-;Ifngr1-/- mice with ~10,000-fold lower dose of bacteria than i.v. infection." (PMID 34423779, 2021). "Another interesting aspect of our mouse model is that both of our mouse KitW-sh/W-sh Ifnar1−/− Ifngr1−/− and KitW-sh/W-sh Ifnar1−/− Ifngr1+/+ were particularly susceptible to infection by the s.c. infection route, which is the natural route of DENV infection." (PMID 34066286, 2021). "Both IRF9 and IFNAR1 deficiency alter liver and macrophage metabolism during infection, but in some cases their impacts differ." (PMID 34237114, 2021). "This anticipated result is an indication of the establishment of infection in the susceptible Ifnar1-/- mice." (PMID 34552587, 2021). "This demonstrates that i.d. infection of Ifnar1-/-;Ifngr1-/- mice with R. parkeri causes systemic infection and can be used as a model for dissemination from the skin to internal organs." (PMID 34423779, 2021). "This study aimed at modeling the inducibility of type 1 interferon receptor subunits 1/2 (IFNAR1/2), mimicking competition between IFNτ and infection-associated interferon α (IFNα), and simulating type 1 interferon pathways in vitro." (PMID 33494350, 2021). "The loss of body weight between days two and three was anticipated, as it indicates establishment of infection of the susceptible Ifnar1-/- mice." (PMID 34552587, 2021). "We also examined select cytokine and chemokine levels in lung and kidney tissues from WT and Ifnar1-/- animals on day 3 post-infection in order to investigate the potential causes for the delay in viral clearance observed in Ifnar1-/- mice." (PMID 32330200, 2020).
infection (continued). "We identified RRV escape variants within 2 days of infection in both Ifnar1-/- and WT mice in the serum and ankle tissues." (PMID 32760128, 2020). "We recently identified that virus-induced hepatocyte-intrinsic IFNAR1 is required for infection-associated metabolic reprogramming of hepatocytes." (PMID 33045014, 2020). "AR IRF7 deficiency was diagnosed in two individuals aged 49 and 50 years, and AR IFNAR1 deficiency was diagnosed in two individuals aged 26 and 38 years, and none of the four patients had a prior history of life-threatening infections." (PMID 32972995, 2020). "Parental LLC1 cells showed near complete protection from VSV-GP infection in contrast to IFNAR1-deficient LLC1 cells that were highly sensitive to VSV-GP infection and killing." (PMID 31530903, 2019). "In line with this, i.c. infection of Ifnar1−/− mice resulted in a rapid onset of weight loss from day 2 post infection." (PMID 31511023, 2019). "In this regard, we observed that infection of Ifnar1-KO mouse myelinating SC causes a profound deterioration and fragmentation of the myelin sheath." (PMID 29976926, 2018). "In the present study, we show that both the historical MR766 and the 2015 Puerto Rican PRVABC59 isolates establish a productive infection in DRG explants obtained from mice deficient in IFNAR1." (PMID 29976926, 2018). "Infection caused a reduction in the proportion of G0 HSPCs in both WT and Ifnar1-/- mice, though a more marked reduction was observed in the absence of type I IFNs." (PMID 30080899, 2018). "WT mice were treated intranasally with identical doses of IFN-α or IFN-λ one day before infection with SeV and co-housed with Ifnar1−/− Ifnlr1−/− double-deficient sentinel mice." (PMID 29651984, 2018). "We found that fetal Tlr4 and Ifnar1 genes show protective effects during the course of infection, opposing the pathogenic action of the maternal counterparts." (PMID 29440369, 2018). "Neutralization of IFNα/β during infection of WT mice resulted in improved BM cellularity and significant protection against infection-induced loss of HSPCs and HSCs relative to isotype control treated mice, similar to observations in Ifnar1-/- mice." (PMID 30080899, 2018). "To mimic this inhibition in mice we have used the type 1 interferon receptor deficient mice (Ifnar1-/-), that have previously been shown to be susceptible to infection by ZIKV." (PMID 30212537, 2018). "Deficiency in IFNAR1 expression renders mice highly resistant to infection by diverse pathogens, including L. monocytogenes." (PMID 28542482, 2017). "Here we used CNS and PNS myelinating cultures from wild type and Ifnar1 knockout mice to examine neuronal and glial tropism and short-term consequences of direct infection with a Brazilian variant of ZIKV." (PMID 28645311, 2017). "The restriction of TBFVs was linked to the intrinsic cellular response to infection, as it was dependent on signaling through both IFNAR1 and STAT1." (PMID 28650973, 2017). "Mice deficient in the type I IFN receptor IFNAR1 are more susceptible to subcutaneous S. pyogenes infection, which is a relevant model of severe invasive infection of the soft tissue." (PMID 28082986, 2016). "We assessed the microbiota composition in the fecal content of WT and Ifnar1-/- mice before PR8 or mock infection and at 9 day post infection (dpi) since the peak weight loss was observed at 9 dpi in WT and Ifnar1−/− mice." (PMID 27149619, 2016). "In our studies, elevated Th1 responses, as a result of IFNAR1-deficiency, occurred relatively transiently within the first week of infection." (PMID 27812214, 2016). "Mice that lack the type I IFNαβ receptor-deficient (Ifnar1-/-) have been shown to be more resistant to infection with L. monocytogenes compared with wild type (WT) mice, as have mice deficient for the downstream transcription factor IRF3." (PMID 26918359, 2016).